INS (insulin)
Diseases named in the same sentence as INS in open-access papers (continued):
Sharing a sentence is not in itself a finding about the gene and the disease.
Obesity (continued). "Comparing with young mice, our aging mice were highly obese and insulin resistant, which was close to young obesity rodent models in phenotype." (PMID 21655268, 2011). "We show that despite its effects to activate p70S6K, a two-fold increase in dietary leucine improves glucose tolerance, prevents hepatic steatosis, reduces obesity-induced adipose tissue inflammation and rescues insulin signaling in muscle, liver and fat." (PMID 21731668, 2011). "Genetically manipulated mice devoid of RIP140 are lean with increased oxygen consumption and are resistant to high-fat diet-induced obesity and hepatic steatosis with improved insulin sensitivity." (PMID 21193034, 2011). "Because leptin influences appetite, energy consumption, adipose synthesis, and insulin function, investigators have explored the use of recombinant leptin as a treatment for obesity." (PMID 21526991, 2011). "We conducted a case-control study to investigate the relationship between the insulin -23Hph and IGF2 Apa polymorphisms and three common pathological phenotypes: T1DM, T2DM and obesity." (PMID 21637566, 2010). "Both that study and another previous report of factor analysis involving fibrinogen reported broadly similar factors to that of our report: obesity/body mass, glucose/insulin/metabolic, inflammation, lipids and blood pressure." (PMID 21029470, 2010). "For example, mice with myeloid cell-specific deletion of IKKβ or JNK1 have significantly improved glucose tolerance and insulin sensitivity despite high-fat diet-induced obesity." (PMID 20814545, 2010). "In T2DM, hypertension and obesity, insulin's vasodilator actions are impaired, probably for a large part because of low NO action." (PMID 20634940, 2010). "Insulin resistant states such as obesity and T2DM are known prothrombotic states characterized by elevated PAI-1 levels." (PMID 20158910, 2010). "Ghrelin, an orexigenic peptide secreted by the stomach, is documented to be inversely correlated to obesity, insulin and IR indexes in children, such as confirmed in our study." (PMID 20537155, 2010). "Animal models indicate that ghrelin antagonists are able to reduce hyperglycemia and adipogenesis, enhance energy expenditure and fat oxidation, stimulate insulin secretion and action, and heighten resistance to diet-induced obesity." (PMID 20798846, 2010). "In this study we investigated the effects of obesity and hyperinsulinemia on ovarian morphology and the hormone profile in insulin-resistant Zucker fatty rats (5, 8, 12 and 16 weeks of age, n = 6-7)." (PMID 20576113, 2010). "11β-HSD1 knockout mice are resistant to diet- induced obesity and have exhibited improved insulin sensitivity." (PMID 20932307, 2010). "Recent studies have shown that overexpression of Igfbp2 protects against the development of obesity and improves insulin sensitivity." (PMID 20808936, 2010). "Although the effects of blueberry extracts in different studies do not indicate a beneficial effect on obesity, it was found that the parameters affected by obesity such as insulin sensitivity and inflammation are attenuated by blueberry supplementation." (PMID 22254051, 2010). "In animal models, deletion of the cerebral leptin-receptor leads to obesity and elevated plasma levels of leptin, glucose, and insulin." (PMID 20871818, 2010). "The insulin -23Hph and IGF2 Apa polymorphisms were genotyped in Romanian patients with T1DM (n = 204), T2DM (n = 215) or obesity (n = 200) and normoponderal healthy subjects (n = 750)." (PMID 21637566, 2010). "On the other hand the Scd1−/− mice in SV129 background are lean, resistant to diet-induced obesity, have increased insulin sensitivity, and increased metabolic rate." (PMID 20808936, 2010). "Tissue lipid accumulation has been associated with obesity-related IR and these are mediated by TAG-derived metabolites that inhibits insulin signal transduction." (PMID 20670429, 2010).
Obesity (continued). "The changing profile of insulin status over the course of T2DM probably further obscured any associations and there was poor consideration of confounding variables such as insulin, obesity, medication, and time since diagnosis." (PMID 20182531, 2010). "First, it is not clear that the magnitude of increase in fasting blood BCAA in obesity or T2DM are of high enough magnitude to trigger mTOR to a level that would negatively impact insulin action in situ." (PMID 21170321, 2010). "Global knockout of SCD1 in mouse increases fatty acid oxidation and insulin sensitivity which makes the animal resistant to diet-induced obesity." (PMID 20920255, 2010). "It was recently demonstrated that TLR4 activation via dietary lipids triggers inflammatory pathway and alters insulin responsiveness in the fat tissue during obesity." (PMID 20339530, 2010). "In this study we tested the possible association between two polymorphisms from the insulin – IGF2 region and T1DM, T2DM and obesity." (PMID 21637566, 2010). "There have been fewer studies with nuts in patients with obesity, the metabolic syndrome, or type-2 diabetes investigating insulin sensitivity or glycemic control besides the lipid profile." (PMID 22254047, 2010). "Many obesity-related factors are responsible, including increased blood levels of insulin/IGF, IL-6, TNF-alpha, and leptin, and decreased blood levels of adiponectin." (PMID 21103795, 2010). "For these reasons, the respective genetic defects in db/db and ob/ob mice mainly combine a pronounced obesity with an insulin-resistance, actually generating a model of metabolic syndrome." (PMID 21318183, 2010). "This is the first study to simultaneously assess the relationship between insulin – IGF2 polymorphisms and T1DM, T2DM and obesity in the Romanian population." (PMID 21637566, 2010). "Our data demonstrate that obesity is linked to increased adipose tissue expressions of CD68 and TNF-α, and that both, CD68 and TNF-α expressions predict insulin sensitivity independently of known confounders." (PMID 21197447, 2010). "But beyond the capacity of adipocytes to secrete these and possibly more proinflammatory cytokines, under circumstances of obesity and/or nutrient overload, adipose tissue macrophages do also provide their counterpart of insulin-resistance inducing cytokines." (PMID 20706689, 2010). "In humans, both obesity and insulin significantly elevate the plasma levels of apelin and this peptide appears to act as a circulating and paracrine hormone." (PMID 20847813, 2010). "Recently, deletions in the region p11.2 of the chromosome 16 encompassing the gene SH2B1, which is involved in the leptin and insulin signaling, have been reported in about 0.5% of children with severe early-onset obesity." (PMID 20540750, 2010). "Polymorphisms in the coding region of the ghrelin gene were suggested to be involved in the aetiology of obesity and to modulate glucose-induced insulin secretion in different ethnic study groups." (PMID 20920174, 2010). "Under-nutrition severely suppressed plasma insulin and leptin during lactation and diet-induced obesity in adult mice, whereas over-nourished mice were phenotypically indistinguishable from those on a control diet." (PMID 20574519, 2010). "It stimulates oxygen consumption, inhibits basal insulin release and glucose tolerance, and this impaired insulin intolerance occurs prior to the onset of hyperphagia and obesity." (PMID 20976162, 2010). "The INSIG2 gene is a good candidate for being related to obesity because of its function in lipid metabolism, particularly in blocking the processing of SREBPs in response to cholesterol or insulin." (PMID 20955599, 2010). "Covey and colleagues report that mice with deletion of leptin receptor in pancreatic β cells and hypothalamus develop obesity, fasting hyperinsulinemia, impaired glucose-stimulated insulin release, and glucose intolerance." (PMID 21113299, 2010).
Obesity (continued). "Mice with a deficiency in both CIDEA and CIDEB have a higher energy expenditure, enhanced insulin sensitivity and a resistance against high-fat-diet-induced obesity and diabetes." (PMID 20649970, 2010). "It has also been reported that elevated vaspin serum concentrations are correlated with obesity and impaired insulin sensitivity, whereas type 2 diabetes appears to abrogate this correlation." (PMID 20847813, 2010). "Some have argued that many free testosterone concentration measurements use a tracer analogue method that is affected by SHBG (sex hormone-binding globulin) levels, which in turn are decreased by obesity and high insulin concentrations." (PMID 19433001, 2009). "The other postulates that the damage causes disinhibition of vagal tone at the pancreatic β-cells, which leads to insulin hypersecretion and obesity." (PMID 19341477, 2009). "Lesions of the ventromedial hypothalamus produce obesity and hyperinsulinemia in rats, while complete vagotomy reverses the obesity and lowers plasma insulin." (PMID 19341477, 2009). "This study has confirmed the previous findings demonstrating positive correlations between serum marker of obesity i.e leptin and insulin and left ventricular mass changes." (PMID 19393079, 2009). "In baboons, insulin sensitivity levels can be evaluated directly with the euglycemic clamp and is highly predicted by adiposity, metabolic markers of obesity and impaired glucose metabolism (i.e. percent body fat by DXA and HbA1c)." (PMID 19389241, 2009). "In contrast to the C57BL/6 mouse model of HFD feeding in which NASH was associated with obesity, T2DM, and hyperlipidemia, the serological profile in the present model provided minimal evidence of hepatic insulin/IGF resistance." (PMID 20034403, 2009). "Fat deposition in the muscle and liver is positively correlated with measures of obesity and negatively with insulin sensitivity." (PMID 19365547, 2009). "Several well-established components of (albeit adult) cardiovascular and metabolic function will be addressed in our study, including obesity, insulin sensitivity, lipid profile and blood pressure." (PMID 19317894, 2009). "In Man, increased protein catabolism has been observed with obesity, related to the resistance of glucose and protein metabolism to insulin and the increased hepatic supply of glucogenic amino acids." (PMID 19826474, 2009). "Obesity has been identified as a major risk factor for such cancer sites as colon, renal, breast, and endometrium, whereas hypertriglyceridemia is relevant to obesity and insulin resistance." (PMID 19690552, 2009). "Though a number of studies have investigated the effects diet-induced obesity on skeletal muscle oxidative capacity and insulin sensitivity, we are unaware of any that relate these changes with alterations in skeletal muscle morphology and functional capacity." (PMID 19806198, 2009). "T2DM seems to result from a complicated interplay of genetic and environmental factors influencing a number of intermediate traits of relevance to the diabetic phenotype (e.g., insulin secretion, insulin action, fat distribution, obesity)." (PMID 19228405, 2009). "Recombinant resistin protein was found to impair insulin action in normal mice and cultured adipocytes, and immunoneutralization of resistin improved insulin action in mice with diet-induced obesity." (PMID 19649297, 2009). "Recent studies have established UCP2 as a key component of beta cell glucose sensing, since it seems to regulate glucose-stimulated insulin secretion, and is also a critical link between obesity, beta cell dysfunction and type 2 diabetes (T2DM)." (PMID 19769793, 2009). "This study confirms and extends information regarding desaturase indices in different lipid pools as well as in relation to obesity and insulin action." (PMID 19712485, 2009).
Obesity (continued). "We recently reported that these SIRT1 activators, like calorie restriction, improve glucose and insulin homeostasis in three models of T2DM: a C57BL/6 mouse diet-induced-obesity model, an ob/ob mouse model and a Zucker fa/fa model." (PMID 19284563, 2009). "Although the animals at day 55 have yet to develop obesity they already show biochemical abnormalities and by day 110 express a phenotype characterized by increased adiposity and altered insulin sensitivity." (PMID 19787071, 2009). "The consequence of this deregulation was, however, to confer greater insulin sensitivity and to protect the mice against diet-induced obesity." (PMID 19030233, 2008). "Adiponectin has been identified as an insulin sensitising adipocyte derived protein, which is decreased in obesity." (PMID 19087258, 2008). "Taken together, the resistance to obesity of the Snord116del males correlates with increased sensitivity to insulin." (PMID 18320030, 2008). "Results from our laboratory showed that phenotype alterations in 129S6 fed the same 40% HFD were more profound when fat feeding was prolonged (15 weeks) and combined obesity, hyperlipidemia, enhanced insulin secretion, glucose intolerance and fatty liver." (PMID 18301746, 2008). "The EGIR has proposed several changes in the definition of the WHO, such as the presence of obesity (waist perimeter ≥ 94 cm in males and ≥ 80 cm in females), fasting plasma insulin determination and altered fasting glycaemia." (PMID 18831772, 2008). "This animal resists diet-induced obesity, has improved glucose and insulin tolerance and demonstrates favorable changes in cytokine expression, including a doubling in adiponectin." (PMID 18269730, 2008). "In this study, BMI was taken as major criteria of obesity and correlation of BMI with different clinical and genetic parameter was seen like waist to hip ratio and hormonal levels (insulin, leptin, glucagon, and growth hormone)." (PMID 20300294, 2008). "The discovery of an adipose-specific secreted protein called ‘resistin’ which circulates in the mouse, with increased levels in obesity, and has effects on glucose homeostasis that oppose those of insulin." (PMID 21876654, 2008). "Scd1 knock-out mice are lean due to increased energy expenditure, show increased insulin sensitivity and are resistant to diet-induced obesity and liver steatosis." (PMID 18590522, 2008). "JNK activity is increased in insulin-resistant states such as obesity and inflammation and can negatively regulate insulin signalling through serine phosphorylation of IRS-1 and impaired activation of Akt." (PMID 19011679, 2008). "Monomeric TRAP, most likely secreted from adipose tissue macrophages, induces hyperplastic obesity with normal adipocyte lipid metabolism and insulin sensitivity." (PMID 18320034, 2008). "We demonstrate that certain macrophages in adipose tissue secrete monomeric TRAP that induces insulin-sensitive obesity by formation of new small adipocytes i.e. hyperplastic obesity." (PMID 18320034, 2008). "Skipping breakfast and eating large dinners affects the way the tissues respond to the influence of insulin and glucagon, ultimately facilitating resistance, a key problem in the development of metabolic syndrome and other obesity-related problems." (PMID 17875273, 2007). "In humans obesity is related to a reduced insulin sensitivity concomitant with an increased incidence of metabolic diseases." (PMID 17931417, 2007). "It has been shown that the transport of insulin across the blood-brain barrier is reduced in dogs with obesity induced by a high-fat diet." (PMID 18030331, 2007). "Obesity, in turn, impacts levels of serum estrogen, insulin, and/or insulin-like growth factor-1, which have all been implicated as possible links between obesity and breast cancer." (PMID 18162139, 2007).
Obesity (continued). "Pairwise analyses revealed that LPCs correlated positively with measures subcutaneous obesity and negatively with insulin sensitivity, while the reverse was found for ether phospholipids." (PMID 17299598, 2007). "Recently, mouse resistin was described as a novel obesity-mediated adipocytokine that impairs glucose homeostasis by affecting both insulin-stimulated glucose uptake in adipose tissue and hepatic glucose production during fasting." (PMID 17183659, 2006). "Insulin resistance, a characteristic of obesity, prevents insulin from taking the sugar from food and distributing it throughout the body for energy." (PMID 17183713, 2006). "Adiponectin, an adipocyte secreted endogenous insulin sensitizer, appears to play an important role not only in glucose and lipid metabolism but also in the development and progression of several obesity-related malignancies." (PMID 16570048, 2006). "Analysis of this subgroup by multiple regression revealed that subregion abdominal fat became the significant obesity-related determinant of GH peak, but still lagged behind fasting insulin and glucose." (PMID 16886956, 2006). "Circulating levels of TNF alpha show a coordinated increase with obesity during the course of gestational diabetes, and at a physiological level, this adipocytokine alters insulin signal transduction and secretion." (PMID 16965635, 2006). "Remarkably, transplantation of Dgat1-/- WAT conferred partial obesity resistance, enhanced glucose disposal after a glucose load, and increased activation of the insulin signaling pathway in WT recipient mice." (PMID 16448557, 2006). "The disruption of the PTPN1 gene in mice results in increased insulin sensitivity, resistance to diet-induced obesity and enables normalization of blood glucose levels." (PMID 16677372, 2006). "Previous studies have provided evidence for the association of leptin with key variables of the metabolic syndrome and with insulin sensitivity, independently of obesity." (PMID 16669997, 2006). "The early stage of the HFF model is useful to examine dislipidemia because the animals lack many confounding factors such as insulin resistance or the impact of elevated FFA or obesity." (PMID 16091142, 2005). "In this pilot study, a LCKD led to significant improvement in weight, percent free testosterone, LH/FSH ratio, and fasting insulin in women with obesity and PCOS over a 24 week period." (PMID 16359551, 2005). "Adiponectin is an adipocyte-specific protein that plays a role in obesity, insulin resistant, lipid metabolism, and anti-inflammation." (PMID 16262911, 2005). "Although there is no universally accepted definition or mechanism, a rough common denominator is the set of five features: obesity (high body weight, BMI and/or waist circumference), high glucose and insulin levels, low HDL, high TAG and high blood pressure." (PMID 16288655, 2005). "In summary, in this pilot study, a LCKD led to significant reductions in weight, percent free testosterone, LH/FSH ratio, and fasting serum insulin in women with obesity and PCOS over a six-month period." (PMID 16359551, 2005). "It is at least plausible that obesity and the features of MetS arise in parallel from disruptions of insulin metabolism (possibly a consequence of high insulin due to chronic high dietary CHO)." (PMID 16288655, 2005). "Obesity is a physiological state that is accompanied by abnormal glucose metabolism and greater insulin resistance." (PMID 15685231, 2005). "In this context it is intriguing that resistin levels are increased in obesity and that insulin-sensitizing agents such as aspirin and rosiglitazone, with disparate primary molecular targets, antagonize resistin induction." (PMID 15578112, 2004). "Together, these data indicate that PPARδ and its ligands comprise a key molecular switch to regulate muscle fiber specification, obesity resistance, insulin sensitivity, and, most surprisingly, physical endurance." (PMID 15328533, 2004).